CD47 (CD47 molecule)
Diseases named in the same sentence as CD47 in open-access papers (continued):
Sharing a sentence is not in itself a finding about the gene and the disease.
atherosclerosis (59 papers, 2017 to 2026). A disease characterized by the build-up of fatty material and calcium deposition in the arterial wall resulting in partial or complete occlusion of the arterial lumen. "The long non-coding RNA myocardial infarction-associated transcript (MIAT), elevated in atherosclerosis patients, interferes with miR-149-5p post-translational processing, thereby increasing CD47 levels." (PMID 39660125, 2024). "We recently reported that global CD47-deficient mice are protected from atherosclerosis, however, myeloid cell-specific CD47 loss augments lesion formation suggesting the importance of cell-specific CD47 blockade in atherosclerosis." (PMID 37476290, 2023). "TNF-α, a pro-inflammatory cytokine associated with atherosclerosis development, promotes CD47 expression on the surface of apoptotic vascular smooth muscle cells." (PMID 38125492, 2023). "It has been reported that a conserved mammalian lncRNA, myocardial infraction–associated transcript (MIAT), upregulates the expression of CD47 by sponging miR-149-5p and shows higher expression in atherosclerosis patients." (PMID 36247464, 2022). "The aggregation of cells caused by CD47 not only plays a role in atherosclerosis but also plays a very important role in the development of cancer." (PMID 32733941, 2020). "For example, loss of CD47, also known as integrin-associated protein, caused increased T-cell activation with increased atherosclerosis in CD47-deficient mice." (PMID 31450823, 2019). "In this study we investigated the effect of CD47-deficiency on atherosclerosis using a model of adeno-associated virus (AAV)-induced hypercholesterolemia." (PMID 31337788, 2019). "In summary, we demonstrate that loss of CD47 causes increased lymphocyte activation that results in increased atherosclerosis." (PMID 31337788, 2019). "This study suggests that dysregulated communication between CD47 and SIRPα may also underlie the progression of atherosclerosis in humans." (PMID 39736852, 2025). "Therefore, it seems that the CD47 expression contributes to the characteristic anti-inflammatory immune profile favoring dyslipidemia and atherosclerosis in ApoE deficiency." (PMID 35418973, 2022). "CD47 is widely expressed on various cells as a kind of “don't eat me” signal, causing “cell aggregation,” reducing macrophage phagocytosis, increasing the necrotic core, and finally promoting atherosclerosis." (PMID 32733941, 2020). "Besides playing an important role in cardiovascular diseases, ischemic strokes caused by atherosclerosis, and tumors, CD47 also plays a significant role in other diseases through different pathways." (PMID 32733941, 2020). "Although we did not observe a difference in Granzyme B production by stimulated NK cells comparing groups, we cannot rule out increased NK cytotoxicity, or increased target cell susceptibility, as a contributing factor promoting atherosclerosis in Cd47−/− mice." (PMID 31337788, 2019). "Enhancing efferocytosis or cholesterol efflux—such as blocking the CD47-SIRPα axis with anti-CD47 antibodies or SHP1 inhibitors—attenuates atherosclerosis." (PMID 41035425, 2026). "Targeting the CD47-SIRPα innate immune checkpoint, a dominant "don't-eat-me" signal, limits atherosclerosis in preclinical models and retrospective human studies." (PMID 42094377, 2026). "Our R@MLP meets this need by simultaneously blocking CD47-SIRPα and stimulating cholesterol efflux, thereby synergistically improving atherosclerosis." (PMID 41035425, 2026). "Elevated levels of TSP-1 impede lymphangiogenesis by activating CD47 in aortic LECs of a mouse model of atherosclerosis." (PMID 40713754, 2025). "Further, deletion of CD47 specifically in LECs augmented lymphangiogenesis and attenuated atherosclerosis in hypercholesterolemic mice." (PMID 41300494, 2025).
atherosclerosis (continued). "The anti-atherosclerosis effects of the integrin-related protein CD47 include the prevention of plaque progression as well as the prevention of plaque rupture and enlargement of the necrotic core." (PMID 41590849, 2025). "unexpectedly found that myeloid cell-specific CD47 knockout Apoe-/- mice exhibited exacerbated atherosclerosis." (PMID 40821806, 2025). "The upregulation of the CD47: SIRPa axis inhibits the clearance of apoptotic cells within plaque lesions, hastening the advancement of atherosclerosis." (PMID 39736852, 2025). "In atherosclerosis, elevated CD47 levels hinder the clearance of apoptotic cells, promoting chronic inflammation and contributing to plaque instability." (PMID 41303525, 2025). "Blockade of the CD47/SIRPa interaction is a novel strategy for the treatment of atherosclerosis, cancer and autoimmune diseases." (PMID 41184328, 2025). "In atherosclerosis, CD47 is upregulated in diseased vascular tissue, where it impairs clearance of apoptotic cells, and CD47-blocking mAbs have shown efficacy in restoring phagocytic clearance and reducing plaque burden in preclinical models." (PMID 41478659, 2025). "Future research is needed to optimize the therapeutic benefits of CD47 inhibition therapy in both cancer and atherosclerosis." (PMID 40821806, 2025). "To date, no experiments have investigated the role of smooth muscle cell CD47 in atherosclerosis, which remains a subject for future research." (PMID 40821806, 2025). "We have previously demonstrated that blockade of TSP1-induced CD47 activation in LECs promotes in vitro lymphangiogenesis and mice with LEC-restricted Cd47 deletion have enhanced arterial lymphatic vessel density and attenuated atherosclerosis." (PMID 41300494, 2025). "Specific knockout experiments provide new insights into the mechanisms by which CD47 inhibition therapy affects atherosclerosis." (PMID 40821806, 2025). "Administration of CD47-blocking antibodies reverses this defect, normalizes vascular tissue clearance, and mitigates atherosclerosis in various mouse models." (PMID 39660125, 2024). "Through the reversal of malignant cell resistance to PrCR, CD47 Ab blockade facilitated the clearance of diseased vascular tissue and promoted its normalization, ultimately ameliorating atherosclerosis." (PMID 38398223, 2024). "AAV8-PCSK9-injected LEC-specific Cd47 knockout mice had reduced atherosclerosis compared with control mice." (PMID 37476290, 2023). "Another example of an approach to restoring efferocytosis is by disrupting “don’t-eat-me” signaling using anti-CD47 or anti-SIRPα monoclonal antibodies to drive resolution and mitigate atherosclerosis." (PMID 36710920, 2023). "LncRNA MIAT positively modulates the expression of the anti-phagocytic molecule CD47 and limits the clearance of apoptotic cells by macrophages, thereby aggravating atherosclerosis." (PMID 36755320, 2023). "Overall, this study demonstrated the therapeutic advantages of PMSN encapsulating anti-CD47 antibodies for atherosclerosis therapy, which holds considerable promise as a new targeted drug delivery platform for efficient therapy of atherosclerosis." (PMID 35118420, 2022). "It has been shown that the increased levels of proinflammatory molecule TNF-α in atherosclerotic tissues upregulates CD47, an important “don't eat me” molecule in the atherosclerosis plaque." (PMID 36247464, 2022). "Overall, our work demonstrated that the platelet membrane-coated MSN loading anti-CD47 antibody was an effective treatment strategy for atherosclerosis." (PMID 35118420, 2022). "Examination of specific immune checkpoints in atherosclerosis has shown that CD47 is critically important in the regulation of macrophage immune reactions." (PMID 35418973, 2022). "The anti-CD47 antibody then normalized the clearance of diseased vascular tissue and further ameliorated atherosclerosis by blocking CD47." (PMID 35118420, 2022).
atherosclerosis (continued). "For example, lncRNA-MIAT can upregulate CD47 expression by inhibiting miR-149-5p expression in advanced atherosclerosis." (PMID 35262384, 2022). "Anti-CD47 treatment in a mouse model of atherosclerosis also leads to significantly improved efferocytosis, increased clearance of apoptotic cells, and further reduced size of atherosclerotic lesions." (PMID 35418973, 2022). "The CD47: SIRPα axis act as a don’t eat me signal and up-regulation of this pathway prevents clearance of apoptotic cells within plaque lesions, accelerating atherosclerosis progression." (PMID 33483751, 2021). "Blocking the CD47–SIRPa interaction then promotes phagocytosis and PrCR, and in atherosclerosis it enhances phagocytic removal of diseased vascular cells and halts disease progression." (PMID 33214223, 2021). "Subsequently, CD47 was reported to be highly expressed in cardiovascular diseases, such as atherosclerosis, ischemia/reperfusion (I/R) injury, and HF." (PMID 34349643, 2021). "Blocking the expression of CD47 and its inhibition with ligands provides a new idea for the treatment of atherosclerosis and cancer." (PMID 32733941, 2020). "They performed that lncRNA-MIAT sponges miR-149-5p to inhibit efferocytosis in advanced atherosclerosis through CD47 up-regulation." (PMID 32090249, 2020). "Taken together, our study indicates that RSV prevents the exacerbation of atherosclerosis induced periodontitis by inhibiting local, systemic and vascular inflammation, as well as the expression of CD47 from arterial smooth muscle cells in mice." (PMID 32286430, 2020). "The apoE−/− mice in atherosclerosis induced by angiotensin II (Ang II) reveal that CD47 expression is significantly increased and concentrated in the necrotic core during atherosclerosis development." (PMID 32733941, 2020). "Among the antiphagocytic signaling molecules, CD47 has been identified as a novel therapeutic target for atherosclerosis by promoting the aggregation of cells." (PMID 32733941, 2020). "Meanwhile, CD47−/− can activate and increase the expression of CD90+ NK cells in CD47-deficient mice, which can produce IFN-γ and further promote atherosclerosis." (PMID 32733941, 2020). "Some inflammatory factors such as TNF-α can promote the expression of CD47 and accelerate the progression of atherosclerosis and plaque formation." (PMID 32733941, 2020). "CD36 and CD47 not only regulate the inflammatory process in atherosclerosis but also regulate angiogenesis in the process of atherosclerosis." (PMID 32733941, 2020). "Several studies have shown that the rate of progression of atherosclerosis of CD47−/− mice was significantly faster than that of wild-type mice." (PMID 32733941, 2020). "As an important inflammation regulatory factor, CD47 plays an important role in inflammation, atherosclerosis, and immune diseases." (PMID 32733941, 2020). "A recent study demonstrated a determinant role of CD47 in atherosclerosis by mediating clearance of diseased macrophages and vascular smooth muscle cells." (PMID 32286430, 2020). "In the late stage of atherosclerosis, the expression of CD47 in aging erythrocytes can reduce erythrocyte phagocytosis and cause the aggregation of cells accelerating atherosclerosis." (PMID 32733941, 2020). "A large number of previous studies have shown that CD47 promotes atherosclerosis by expressing the “don't eat me” signal to mediate the endocytosis of macrophages." (PMID 32733941, 2020). "In atherosclerosis, CD47 expression is significantly elevated and concentrated in the necrotic core of the plaque." (PMID 32733941, 2020). "Anti-CD47 antibodies can reduce atherosclerosis, which confirms that CD47 is closely related to the formation of atherosclerotic plaques." (PMID 32733941, 2020). "This suggests that the atherosclerosis phenotype observed in Cd47−/− mice is due to immune activation." (PMID 31337788, 2019).
atherosclerosis (continued). "Among the antiphagocytic signal molecules, CD47 has been identified as a novel therapeutic target for treating atherosclerosis by promoting efferocytosis." (PMID 30755588, 2019). "During the preparation of this manuscript a study was published that demonstrated that injections of anti-CD47 mAb (clone: MIAP410) resulted in reduced atherosclerosis due to increased efferocytosis of lesional apoptotic cells." (PMID 31337788, 2019). "Loss of Cd47 led to an enrichment of CD90+CD27+ IFN-γ producing NK cells and depletion of NK cells blocked the increased atherosclerosis observed in Cd47−/− mice." (PMID 31337788, 2019). "Here, using single-cell transcriptomics, monocyte fate mapping, and functional analyses across complementary preventive and interventive murine atherosclerosis models, we demonstrate that CD47 blockade fundamentally reprograms the myeloid landscape of established lesions." (PMID 42094377, 2026). "Similarly, macrophage-targeted single-walled carbon nanotubes loaded with CD47-SIRPα signaling inhibitors can enhance efferocytosis in lesion macrophages and reduce atherosclerosis." (PMID 41293421, 2025). "The expression of SIRP α and CD47 is increased in human atherosclerosis." (PMID 40821806, 2025). "In atherosclerosis, CD47 overexpression on apoptotic cells inhibits SIRPα-dependent macrophage efferocytosis, leading to accumulation of necrotic debris and heightened inflammation, its inhibition reduces plaque progression and necrotic core size in murine models such as ApoE−/− mice." (PMID 41303525, 2025). "It has previously been reported that the CD47 level is elevated in mouse models of atherosclerosis." (PMID 38398223, 2024). "CD47−/−/ApoE−/− mice are protected from atherosclerosis, and systemic inhibition of SIRPα -mediated signaling appears more effective in reducing the necrotic core area in murine atherosclerosis models compared to global CD47 inhibition." (PMID 39926714, 2024). "CD47 has been demonstrated to inhibit efferocytosis in the context of atherosclerosis." (PMID 39660125, 2024). "In the advanced stage of atherosclerosis, characterized by the accumulation of arterial smooth muscle cells in the atherosclerotic necrotic core due to impaired clearance, we assessed the level of CD47 in aortic roots." (PMID 38892314, 2024). "The eighth lecture, “CD47 Deletion in Lymphatic Endothelium Augments Arterial Lymphangiogenesis and Attenuates Atherosclerosis”, was delivered by Dr. Bhupesh Singla, Assistant Professor, Department of Pharmaceutical Sciences, The University of Tennessee Health Science Center." (PMID 37476290, 2023). "Furthermore, it has been shown that CD47 expression level increases continuously in the process of atherosclerosis development and anti-CD47 antibody reduce vascular inflammation in the carotid arteries of participants." (PMID 38125492, 2023). "Altogether, these findings identify LEC CD47 as a potential therapeutic target in atherosclerosis." (PMID 37476290, 2023). "Since atherosclerosis is the basis of most cardiovascular diseases, targeting CD47 signaling may also provide a promising approach to the prevention and treatment of cardiovascular diseases." (PMID 38125492, 2023). "Similarly, macrophage-targeting single-walled carbon nanotubes loaded with a chemical inhibitor of CD47-SIRPα signaling enhances efferocytosis in lesional macrophages and reduces atherosclerosis." (PMID 36710920, 2023). "It is still unclear whether necroptotic macrophages in atherosclerosis also express CD47, which restricts phagocytosis and thereby promotes disease progression." (PMID 35418973, 2022). "Therefore, CD47 protein was identified as a new target for the prevention and treatment of atherosclerosis." (PMID 35118420, 2022). "Additionally, studies have shown that atherosclerotic mouse models treated with CD47 blocking antibodies improved atherosclerosis by enhancing clearance of dead vascular tissue and reversing impaired efferocytosis." (PMID 36247464, 2022).
atherosclerosis (continued). "Work from the Leeper laboratory has demonstrated that anti-CD47 (pro-efferocytic therapy), delivered systemically or in a macrophage-specific nanotube therapy, holds promise in animal models of atherosclerosis, while human data has suggested anti-CD47 therapy reduces carotid artery inflammation." (PMID 35498030, 2022). "CD47 has been found to be upregulated in human atherosclerotic plaques compared to non-atherosclerotic vascular tissue and administration of anti-CD47 antibodies ameliorates atherosclerosis by reversing defects in efferocytosis, normalizing the clearance of diseased vascular tissue." (PMID 33920030, 2021). "Mice lacking CD47 are more susceptible to atherosclerosis, and treatment with an inhibitory antibody against CD47 induces the same effect as that of decreasing efferocytosis." (PMID 33854480, 2021). "As macrophages are important players in development of atherosclerosis we cannot exclude their contribution to the observed phenotype, especially since the SIRPα counter-receptor CD47 appears involved in pathogenesis of atherosclerosis through inhibition, e.g., macrophage efferocytosis." (PMID 33162986, 2020). "Hypoxia induces the expression of HIF-1-dependent CD47, which interacts with VEGF to activate antimacrophage phagocytosis, causing hypercytosis, promoting the formation of a plaque necrotic core and accelerating the progression of atherosclerosis." (PMID 32733941, 2020). "The previous view was that in atherosclerosis, an increased expression of CD47 made macrophages resistant to programmed cell removal by expressing the “don't eat me” signal, causing hypercytosis, increasing the necrotic core of the plaque, and promoting the progress of atherosclerosis." (PMID 32733941, 2020). "Collectively, these data indicate that effects of RSV on CD47 expression may partly account for prevention of atherosclerosis by RSV in vivo." (PMID 32286430, 2020). "Although T cell numbers were reduced in lymphoid tissue and in atherosclerotic lesions, it remained possible that increased activity of remaining T cells could be responsible for the increased atherosclerosis observed in Cd47−/− mice." (PMID 31337788, 2019). "In summary, we demonstrate an unexpected protective role for CD47 in murine atherosclerosis." (PMID 31337788, 2019). "Altogether this experiment strengthens the notion that the mechanism by which CD47-deficient NK cells promote development of atherosclerosis is by cytokine production and not through excessive cytotoxic ability." (PMID 31337788, 2019). "Blockade of CD47 (clone MIAP410) in Apoe−/− mice fed HCD and given angiotensin II was effective in reducing atherosclerosis and necrotic core formation, however, the atheroprotective effect of anti-CD47 mAb was only modest in a standard model of atherosclerosis akin to that used in our study." (PMID 31337788, 2019). "We tested whether activation T cells explained the increased atherosclerosis in Cd47−/− mice by antibody depletion of CD4+ and CD8+ T cells." (PMID 31337788, 2019). "Interestingly, administration of a blocking CD47 antibody reversed this effect, stimulating efferocytosis and reducing atherosclerosis, making CD47 a potential drug target for the clinic." (PMID 31998312, 2019). "Our data suggest that the primary effect of CD47-deficiency on atherosclerosis is not related to efferocytosis in the plaque but rather due to dysregulation and activation of NK cells." (PMID 31337788, 2019). "Recently published studies found that CD47-blocking antibodies could restore phagocytosis and prevent atherosclerosis." (PMID 29561847, 2018). "Inhibition of CD47 with an anti‐CD47 antibody has been shown to reverse this pathology, removing apoptotic debris from atherosclerotic plaques, which may be useful for treating atherosclerosis in the elderly." (PMID 39748782, 2025).